BMI1 (BMI1 proto-oncogene, polycomb ring finger)
Diseases named in the same sentence as BMI1 in open-access papers (continued):
Sharing a sentence is not in itself a finding about the gene and the disease.
colorectal cancer (52 papers, 2009 to 2025). A primary or metastatic malignant neoplasm that affects the colon or rectum. "Basically, the mechanism involved in PP2A‐mediated BMI1 ubiquitination and proteasomal degradation associated with colorectal cancer; hence, HTfNPs exerted notable therapeutic effects as an anticancer therapeutic to target colorectal cancer." (PMID 39801754, 2025). "Importantly, the treatment of primary colorectal cancer xenografts with a small-molecule acting as a Bmi1 inhibitor, resulted in the loss of cancer-initiating cells, with a consequent inhibition of tumor growth." (PMID 29652830, 2018). "To delineate the correlation between the expression patterns of CSN5, BMI1, and PD‐L1 in the tumor tissues of colorectal cancer patients and their prognostic implications, we analyzed overall survival data from the TCGA colorectal cancer database." (PMID 39721027, 2025). "BTF3 also regulates proto-oncogene BMI1 to enhance epithelial-mesenchymal transition and stem cell-like traits to promote colorectal cancer development." (PMID 40651979, 2025). "Overall, elevated BMI1 expression was correlated with an adverse prognosis in colorectal cancer patients." (PMID 39721027, 2025). "Therapeutic inhibition of Bmi-1 was first described in a primary colorectal cancer xenograft model, where it inhibited CSC self-renewal and thus abrogated their tumorigenic potential." (PMID 36726797, 2023). "In colorectal cancer cells, epigallocatechin-3-gallate, a polyphenol phytochemical, was discovered to inhibit the expression of Notch, BMI1, and EZH2 with an upregulation of the expression of miR-145, miR-34a, and miR-200c, thus reducing tumor growth." (PMID 36499676, 2022). "USP22 acts as an oncogene in colorectal cancer by activating BMI1, which, in turn, activates the INK4a/ARF pathway and Akt signaling pathway." (PMID 35935969, 2022). "BMI1 inhibitors suppress the invasion proliferation as well as migration of colorectal cancer cells, which also exhibit similar effects on other types of tumors." (PMID 34753387, 2021). "In colorectal cancer, miR-128-3p reverses oxaliplatin resistance in colorectal cancer through the downregulation of Bmi1 and MRP5, two genes involved in oxaliplatin-induced EMT." (PMID 34003341, 2021). "It is noteworthy that RNF220 regulates BMI1 expression via USP22, therefore, USP22-BMI1 axis was validated in this study to function in colorectal cancer progression." (PMID 34753387, 2021). "It has been proved that colorectal cancer cells are highly dependent on BMI-1, which works as the regulator maintaining the viability and proliferation of colorectal cancer cells and the self-renewal of CICs." (PMID 31640758, 2019). "QW24 had significant effect on suppressing colorectal cancer stem-like cell growth in vitro by down-regulating BMI-1 protein." (PMID 31640758, 2019). "Increasing studies have proved BMI-1 as an important therapeutic target in different cancers including colorectal cancer." (PMID 31640758, 2019). "BMI-1, a critical regulator of self-renewal in the maintenance of CICs, is identified as a potential target for colorectal cancer therapy." (PMID 31640758, 2019). "This conclusion was further supported by another study showing that the targeting of Bmi1—a canonical regulator of self-renewal—inhibits the ability of colorectal cancer stem cells to self-renew, inducing the abrogation of their tumorigenic potential." (PMID 29652830, 2018). "PTC 209 was discovered by high throughput screening of compounds utilizing the gene expression modulation by small molecules (GEMS) technology and shown to downregulate Bmi1 expression in colorectal cancer initiating cells." (PMID 28418883, 2017). "B cell-specific Moloney murine leukemia virus insertion site 1 (Bmi1) is frequently overexpressed in human sporadic colorectal cancer and the degree of upregulation correlates with disease progression and is predictive of poor patient survival." (PMID 28160571, 2017).
colorectal cancer (continued). "For example, CSCs properties in human colorectal cancer are highly dependent on Bmi1, as downregulation of Bmi1 inhibits their self-renewal and abrogates their tumorigenic potentials in vitro and in animal models." (PMID 29200967, 2017). "More recently, PTC-209, a small molecule inhibitor of BMI1 was shown to target self-renewal of colon CSCs and inhibit colorectal cancer." (PMID 27105531, 2016). "BMI1 is a marker for intestinal stem cells, and a BMI1 inhibitor has been found to inhibit colorectal cancer stem cells." (PMID 26349457, 2016). "In this study, effects of curcumin and two analogs (bisdemethoxycurcumin and dimethoxycurcumin) on BMI1 expression were evaluated in DLD‐1 colorectal cancer cells." (PMID 27550987, 2016). "This is different from the findings in other gastrointestinal tumor types such as colorectal cancer and pancreatic cancer, where patients with low Bmi-1 expression had a better survival outcome." (PMID 26894855, 2016). "In conclusion, we showed that combined expression of PcG proteins EZH2, BMI1 and SUZ12 and their associated histone modification H3K27me3 has prognostic value in our colorectal cancer study cohort." (PMID 25243792, 2014). "In search for new biomarkers, we investigated the expression of Polycomb-group (PcG) proteins EZH2, BMI1 and SUZ12 and associated histone modification H3K27me3 in colorectal cancer." (PMID 25243792, 2014). "In this study, we investigated the expression of three PcG proteins (EZH2, BMI1 and SUZ12) and associated histone modification H3K27me3 in colorectal cancer tissues." (PMID 25243792, 2014). "Both miR-15b and miR-200b regulate chemotherapy-induced EMT by downregulating Bmi1 in tongue squamous cell carcinomas, and miR-218 inhibits cell proliferation and cycle progression and promotes apoptosis by downregulating Bmi1 in colorectal cancer cells." (PMID 24312366, 2013). "More importantly, researchers found that circ_001680 could promote the number of cancer stem cells in colorectal cancer by regulating Bmi1 through miR-340." (PMID 36983561, 2023). "Bmi-1 may also regulate the TLR4/MD2/MyD88 complex-mediated NF-κB signaling pathway to participate in colorectal cancer cell EMT." (PMID 35897796, 2022). "The radioresistant function of BMI1 was also observed in colorectal cancer cells, and the overexpression of Kruppel-like factor 4 partially confers the radiosensitized phenotype in BMI1-knockdown colorectal cancer cells." (PMID 36362068, 2022). "USP22, an oncogene, could actively and effectively participate in the regulation of the cell cycle through the INK4a/ARF signaling pathway mediated by Bmi-1 in human colorectal cancer cells." (PMID 35897796, 2022). "Moreover, Bmi-1 promote colorectal cancer migration and EMT in an inflammatory microenvironment by regulating TLR4/MD2/MyD88 complex-mediated NF-κB signaling pathway." (PMID 35897796, 2022). "Our study discovered USP22 combined with BMI1, and thus accelerating stemness of colorectal cancer." (PMID 34753387, 2021). "All these results illustrated the pro-tumorigenic effects of RNF220/USP22/BMI1 signal pathway on proliferation and stemness of colorectal cancer, providing novel insights into RNF220 as clinical therapeutic candidates for future drug design and development targeting colorectal cancer." (PMID 34753387, 2021). "Additionally, targeting BMI1 by using a small molecule, PTC-209, has also demonstrated efficacy against CSCs in models of colorectal cancer through decreasing BMI1 protein levels." (PMID 32754274, 2020). "We describe here that QW24, a novel synthetic small molecule compound, impairs the self-renewal of CICs and inhibits the growth and metastasis of colorectal cancer in xenograft models by down-regulating BMI-1 significantly through autophagy-lysosome protein degradation pathway." (PMID 31640758, 2019). "As reported, BMI-1, the primary regulator of colorectal CICs, could be the critical target for colorectal cancer therapy." (PMID 31640758, 2019).
colorectal cancer (continued). "Therefore, targeting the BMI-1-related self-renewal machinery provides the basis for a new therapeutic approach in the treatment of colorectal cancer." (PMID 31640758, 2019). "Moreover, specific NO depletion also decreased the expression of CSC-related proteins in human colorectal cancer cells such as β-catenin and Bmi1, impairing the CSC phenotype." (PMID 29329541, 2018). "Recently, others have identified a small molecule inhibitor of BMI1 (PTC-209) that demonstrates differential cytotoxicity against human colorectal cancer cells while having minimal cytotoxic effects on human peripheral blood mononuclear cells and hematopoietic stem cells at similar concentrations." (PMID 26110620, 2015). "Using immunohistochemical staining (IHC) and semi-automated scoring, we studied the expression of PcG proteins EZH2, BMI1 and SUZ12 and their associated histone modification H3K27me3 in a cohort of 247 TNM stage I-III colorectal cancer patients, in correlation with clinical outcome." (PMID 25243792, 2014). "In order to obtain more information about epigenetic pathways with potential prognostic value in colorectal cancer, we performed multivariate survival analyses using combined expression data of multiple PcG proteins (EZH2, BMI1 and SUZ12) and their associated histone modification H3K27me3." (PMID 25243792, 2014). "Furthermore, Bmi1 is overexpressed in CRC samples associated with degree of differentiation, status of lymph node metastasis, and TNM staging in colorectal cancer." (PMID 23363002, 2013). "Moreover, miR-340 could target BMI1, and the ectopic upregulation of BMI1 partially reversed the effect of miR-340 on the growth and migration of colorectal cancer." (PMID 36769373, 2023). "miR-128a increases intracellular reactive oxygen species levels by targeting Bmi-1, which inhibits the growth of medulloblastoma cells and miR-218 inhibits cell proliferation and cell cycle progression and promotes apoptosis by downregulating Bmi-1 in colorectal cancer cells." (PMID 35898889, 2022). "Interestingly, miR-200c might act protectively against colorectal cancer through the BMI1 gene complex." (PMID 33806327, 2021). "In addition, Bmi1 expression is dysregulated in preneoplastic colorectal epithelium and overexpression correlates with malignant progression, supporting a role for Bmi1 in human colorectal cancer progression." (PMID 19568234, 2009). "MiR-485-5p can regulate the O-GlcNAcylation level and the stability of Bmi-1 by inhibiting OGT, and then inhibit the proliferation of colorectal cancer cells." (PMID 35897796, 2022). "In another study, exosome-mediated miR-128-3p delivery was demonstrated to inhibit oxaliplatin-induced epithelial–mesenchymal transition (EMT) and enhanced oxaliplatin response through negative regulation of Bmi1 and MRP5 in colorectal cancer cells." (PMID 34017681, 2021). "As a potential anti-inflammatory target, BMI1 regulates invasion and EMT of colorectal cancer cells via TLR4/MD-2 MyD88 complex-mediated NF-κB signaling pathway." (PMID 33927214, 2021). "Meanwhile, in colorectal cancer, miR-218 is proved to target pro-tumorigenesis gene MACC1 and BMI-1 to inhibit CRC development." (PMID 29977158, 2018). "In colorectal carcinoma, USP22 promoted cell proliferation by activating BMI1-mediated INK4a/ARF pathway and Akt pathway." (PMID 28415621, 2017). "More importantly, BMI1 promotes CSC properties and therapy resistance in breast, prostate, lung and colorectal cancers." (PMID 27105531, 2016). "In our study, we found that CCL21 can upregulate the expression of P-glycoprotein (P-gp) and stem cell property markers such as Bmi-1, Nanog, and OCT-4 in colorectal cancer (CRC) HCT116 cells and then improve the cell survival rate and mammosphere formation." (PMID 27057280, 2016). "Recently, PTC-209 a small molecule inhibitor of BMI1 selected by GMS technology was reported to downregulate BMI1 and colon cancer stem cell (CSC) phenotype in a colorectal cancer model." (PMID 27105531, 2016).
colorectal cancer (continued). "The small molecule BMI1 inhibitor PTC-209 has been shown to decrease BMI protein expression and induce cytotoxicity in human colorectal cancer cells, but its effects on canine cancer cells or OSA cells has not previously been evaluated." (PMID 26110620, 2015). "Bmi1, member of the PRC1, has also been found to be a candidate target gene of miR-203, where ectopic expression of miR-203 in pancreatic and colorectal cancer cells induced apoptosis and repressed cell growth." (PMID 25004126, 2014). "Among the top genes emerging from limma analysis, we found four genes particularly related to cancer stemness and CRC CSCs: besides the pluripotency factor KLF4, we found three genes were specifically related to colorectal cancer stemness and self renewal, i.e., AXIN2, LGR5 and BMI1." (PMID 36077264, 2022). "Although PTC209 does not bind to BMI1, it reduces both BMI1 and H2AK119ub1 levels and inhibits the self-renewal of colorectal cancer-initiating cells, resulting in the abrogation of colorectal tumors." (PMID 36105358, 2022). "The inhibition of colorectal cancer cell growth by QW24 was reversed by BMI-1 overexpression with lentivirus infection, which suggests that colorectal cancer cells are dependent on BMI-1 for maintaining growth." (PMID 31640758, 2019). "Study also showed that LDL could enhance stemness by increasing stemness-related genes, such as Sox2, Oct4, Nanog, and Bmi1 in colorectal cancer cells, increased ROS levels that can further activate MAPK pathways, and stimulated intestinal inflammation and colorectal cancer." (PMID 35251975, 2022). "The specificity of QW24 towards BMI-1 was demonstrated by the fact that normal cells expressing low levels of BMI-1 were nonresponsive while colorectal cancer cells expressing higher BMI-1 showed a dose-dependent decrease in cell viability upon treatment with QW24." (PMID 31640758, 2019). "Our preclinical data show that QW24 exerts potent anti-tumor activity by down-regulating BMI-1 and abrogating colorectal CICs self-renewal without obvious toxicity in vivo, suggesting that QW24 could potentially be used as an effective therapeutic agent for clinical colorectal cancer treatment." (PMID 31640758, 2019).
colon carcinoma (50 papers, 2009 to 2025). "Several target genes induced by HES1 in CRC cells have been identified including the oncogene BMI1, which promotes invasion and migration of colon cancer cells." (PMID 38459621, 2024). "Elevated expression of Bmi1 in colon cancer patients is important for the self-renewal of colon cancer stem cells and promotes the invasion and migration of colon cancer cells." (PMID 30679589, 2019). "Here, mRNA expressions were analyzed for TETs, LGR5 and BMI1 in CSCs isolated from human colon cancer samples." (PMID 31057717, 2019). "Correspondingly, the expression levels of stem cell-associated genes, including OCT4, Lin28, Lgr5, KLF, Bmi-1, CD44 and SOX2, increased sharply in colon cancer cells upon treatment with exosomes from BM-MSCs or exosomal miR-142-3p." (PMID 30220706, 2018). "BMI1 interacts with several signaling pathways including Notch and Wnt, which are important in colon cancer and chemoresistance." (PMID 29416778, 2018). "Fast-cycling colon cancer stem cells express CD133, while slow-cycling colon cancer stem cells express Bmi1." (PMID 29652830, 2018). "The IL-32θ-induced inhibition of STAT3 results in the downregulation of ZEB1, Bmi1 and also upregulation of E-cadherin signaling in colon cancer cells." (PMID 26824417, 2016). "KLF4 directly represses BMI1 transcription, and thereby regulates BMI1, which is required for colon cancer proliferation." (PMID 27314328, 2016). "By silencing Bmi-1 with RNAi in Hes1-expressing cells, we found that Bmi-1-silencing abrogated Hes1 protection of colon cancer cells from apoptosis, reduced the accelerated cell growth and Akt activation induced by Hes1." (PMID 26452029, 2015). "Taken together, our results indicate that Hes1 plays a quantitative role in the development and progression of colon cancer and suggest a mechanism that links Hes1 to Bmi-1/PTEN/Akt/GSK3β pathway." (PMID 26452029, 2015). "In this study, we found that Bmi-1 was up-regulated in colon cancer tissues and expressed positively correlated with the expression of Hes1." (PMID 26452029, 2015). "Transwell and Boyden assays indicated that inhibition of Bmi-1 reduced the migratory/invasive phenotype of Hes1-expressing colon cancer cells, which was confirmed by in vivo experiments." (PMID 26452029, 2015). "Results showed that Hes1 and Bmi-1 were upregulated in the colon cancer tissue compared with the normal samples." (PMID 26452029, 2015). "Together, these results demonstrate that Bmi-1 is important in mediating the cell growth promotion, Akt activation and antiapoptotic function of Hes1 in colon cancer cells." (PMID 26452029, 2015). "PTEN also reduced the invasive phenotype and cytoskeleton reorganization of Bmi-1-expressing colon cancer cells and restored the Bmi-1-induced EMT phenomenon in cancer cells." (PMID 26452029, 2015). "In particular, collagen type I inhibited cell differentiation, increased clonogenicity and promoted expression of CD133 and Bmi1, indicating that it promoted expression of a stem cell-like phenotype in colon cancer cells." (PMID 24921652, 2014). "Next, we assessed the different relations between Bmi1 and miR-30e* expression in gastric and colon cancer cell lines which were co-cultured with macrophages purified from human monocytes." (PMID 24312366, 2013). "The colon cancer derived tumour spheres obtained in this study were evaluated for expression of a panel of stem cell markers, including BMI-1, nestin (NES), and musashi-1 (MSI-1)." (PMID 20332776, 2010). "Authors have found that collagen type I inhibited cell differentiation, increased clonogenicity and promoted expression of CD133 and Bmi1, indicating that it promoted expression of a stem cell-like phenotype in colon cancer cells." (PMID 20630067, 2010).